FOLR1 (folate receptor alpha)
Diseases named in the same sentence as FOLR1 in open-access papers (continued):
Sharing a sentence is not in itself a finding about the gene and the disease.
gastric cancer (continued). "The high percentage of positivity for FOLR1 and FOLR2 expressions in gastric cancer tissues (82.76% and 70.69%, respectively) underscores the potential role of these receptors in gastric cancer biology." (PMID 38915965, 2024). "While our study provides important insights into the expression and implications of FOLR1 and FOLR2 in gastric cancer, it has certain limitations." (PMID 38915965, 2024). "The statistical analysis demonstrated significant differences in the expression of FOLR1 and FOLR2 between the diffuse and intestinal histological types of gastric cancer." (PMID 38915965, 2024). "The study revealed high expression rates of FOLR1 and FOLR2 in gastric cancer tissues, at 48 (82.76%) and 41 (70.69%) respectively." (PMID 38915965, 2024). "In this context, our study focused on the immunohistochemical expression of FOLR1 and FOLR2 in gastric cancer patients, aiming to elucidate their roles in the disease's pathogenesis and potential as prognostic markers or therapeutic targets." (PMID 38915965, 2024). "Our study objective was to evaluate the expression pattern of FOLR1 and FOLR2 in gastric cancer patients' tissue and blood specimens and correlate the results with the clinicopathological parameters." (PMID 38915965, 2024). "Overall, our findings support the idea that FOLR1 and FOLR2 could serve as potential targets for the development of novel therapies for gastric cancer." (PMID 38915965, 2024). "Another study revealed that Folate receptor 1 (FOLR1) CAR T-cells could detect and kill FOLR1-positive gastric cancer cells." (PMID 36153626, 2022). "The results confirmed that FOLR1 CAR T-cells could recognize and exhibit anti-tumor activity in FOLR1-positive gastric cancer cells." (PMID 31936611, 2020). "To evaluate the effect of FOLR1-CAR against gastric cancer (GC) cells, we divided them into FOLR1-positive and FOLR1-negative cells." (PMID 29874279, 2018). "There is a lack of comprehensive studies investigating the roles of FOLR1 and FOLR2 in gastric cancer." (PMID 38915965, 2024). "In this study, we designed FOLR1-CAR composed of anti-FOLR1 scFv, CD28 and CD3ζ and evaluated the antitumor activity of CAR-mediated T cells against FOLR1 positive and negative gastric cancer cells." (PMID 29874279, 2018).
lung adenocarcinoma (14 papers, 2012 to 2026). A carcinoma that arises from the lung and is characterized by the presence of malignant glandular epithelial cells. "The association between folate receptor alpha expression and clinical outcome was also evaluated on a tissue microarray created from formalin fixed paraffin embedded specimens from patients with surgically resected lung adenocarcinoma." (PMID 22547449, 2012). "Consistently, in vivo xenograft experiments further corroborated the tumor-suppressive role of FOLR1 in lung adenocarcinoma." (PMID 42122127, 2026). "FOLR1 (Folate Receptor Alpha) is overexpressed in a subset of lung adenocarcinomas, supporting tumor cell proliferation through folate uptake." (PMID 40565055, 2025). "Folate receptor alpha expression was shown to have a high discriminatory capacity for lung adenocarcinomas versus squamous cell carcinomas." (PMID 22547449, 2012). "We used flow cytometry to validate lung adenocarcinoma cells, normal epithelial cells, and macrophages with cell markers (EPCAM, FOLR1, and CD163)." (PMID 36249427, 2022). "A promising molecular target in NSCLC is the folate receptor alpha (FRα), which is highly overexpressed in approximately 74% of lung adenocarcinomas, while being largely absent or minimally expressed in normal tissues." (PMID 40958098, 2025).
triple-negative breast carcinoma (14 papers, 2015 to 2026). An invasive breast carcinoma which is negative for expression of estrogen receptor (ER), progesterone receptor (PR), and human epidermal growth factor receptor 2 (HER2). "The expression of the folate receptor alpha (FRα) is significantly increased in patients with triple-negative breast cancer and is therefore, a potential biomarker and therapeutic target." (PMID 33802531, 2021). "In this direction, we developed folate-functionalized DNA origami that effectively targets and delivers doxorubicin (DOX), a well-known anticancer drug to the folate receptor alpha (FOLR1) expressing triple-negative breast cancer (TNBC) cells in vitro." (PMID 34485245, 2021). "To this end, we show that altering FOLR1 expression by shRNA knockdown can influence the growth of triple negative breast cancer cells." (PMID 25816016, 2015). "Given that triple negative breast cancer is a heterogeneous disease, it is tempting to speculate that tumors expressing high levels of FOLR1 represent a specific subtype." (PMID 25816016, 2015).
endometrial cancer (12 papers, 2013 to 2025). Primary or metastatic malignant neoplasm involving the endometrium (mucous membrane that lines the endometrial cavity). "Folate receptor alpha (FR-alpha) seems to play a key role in carcinogenesis, such as in endometrial cancer, whereas in normal and precancerous cells it is of limited expression." (PMID 32604857, 2020). "One such biomarker is folate receptor alpha (FRA), a glycosylphosphatidylinositol (GPI)-anchored protein involved in folate transport into cells that is expressed in breast, lung, clear cell renal, ovarian and endometrial carcinomas, and non-small cell lung adenocarcinoma." (PMID 23590973, 2013).
non-small cell lung carcinoma (12 papers, 2012 to 2023). A group of at least three distinct histological types of lung cancer, including non-small cell squamous cell carcinoma, adenocarcinoma, and large cell carcinoma. "The goal of the present study was to evaluate the expression of folate receptor alpha in non-small cell lung cancer specimens to determine its frequency of expression and its potential for prognosis." (PMID 22547449, 2012).
autism spectrum disorder (10 papers, 2016 to 2025). A spectrum of developmental disorders that includes autism, and Asperger syndrome. "Maternal folate receptor alpha autoantibodies (FRAA) were associated with isolated increased fetal nuchal translucency and subsequent autism spectrum disorder (ASD) in offspring." (PMID 41272990, 2025). "The folate receptor alpha autoantibodies (FRAAs) are associated with cerebral folate deficiency (CFD) and autism spectrum disorder (ASD)." (PMID 38392599, 2024). "Several authors report an increased frequency of serum auto-antibodies against folate receptor alpha (FRAA) in autism spectrum disorder children." (PMID 34440744, 2021). "Our study suggests that FOLR1-related CFD should be considered in cases with febrile convulsions, developmental delay, ataxia, autism spectrum disorder, acquired microcephaly, and MRI findings of white matter involvement and cerebellar atrophy." (PMID 40218241, 2025).
prostate carcinoma (9 papers, 2018 to 2026). A carcinoma that arises from epithelial cells of the prostate gland. "Regarding serum folate receptor alpha, it was significantly higher in the prostate cancer group than the control group with median values 1686.4 pg/ml and 437.2 pg/ml respectively (P < 0.001)." (PMID 40830177, 2025). "The study aimed to assess the potential role of Thymidine Kinase one (TK1) and folate receptor alpha (FORα) in prostate cancer." (PMID 40830177, 2025). "In prostate cancer cells, Folr1 mRNA expression was 329- and 107-times higher in TRAMP-C1 and TRAMP-C2 cells, respectively, when compared to RM-1 cells." (PMID 29482561, 2018). "In contrast, folate-conjugated miR-34a lacked efficacy in prostate cancer owing to absent FOLR1 expression, underscoring the necessity of tumor-specific targeting ligands for clinical translation." (PMID 41374949, 2025). "The anti-proliferative activity of EGCG against prostate cancer cells was increased significantly following treatment with the targeted NPs, particularly in the case of the PSMA+ cells that express higher levels of FOLR1." (PMID 38004545, 2023).
colon cancer (8 papers, 2010 to 2024). "Recent studies have indicated that miR-29b expression inhibits cell viability and stimulates cell apoptosis in human cancers, including colon cancer, through the suppression of FOLR1 expression." (PMID 35406629, 2022). "In colon cancer, miR-29b inhibited cell growth and chemoresistance to oxaliplatin via targeting FOLR1." (PMID 33601338, 2021). "In previous studies on tumor chemotherapy drug resistance, miR-29b was found to reverse Oxa resistance of CRC cells by targeting the SIRT1/ROS/JNK pathway, moreover, it can also target FOLR1 to inhibit cell growth of colon cancer cells and increases cell sensitivity to Oxa." (PMID 32760217, 2020). "A significant overlap was detected with several relevant gene families, including colon cancer progression (e.g., FN1, IGBP3, PLAUR and TIMP1; P=0.00052), tumour cell apoptosis (e.g., BID, TNFRSF21, PHLDA1 and NOTCH1; P=1.46 × 10–6) and cell proliferation (e.g., CTGF, SPP1, FOLR1 and SPARC)." (PMID 21119668, 2010).
cerebral folate deficiency (7 papers, 2016 to 2025). "Disruptions in folate transport at this interface, particularly caused by mutations in the FOLR1 gene or the presence of FRα autoantibodies, lead to reduced folate levels in the cerebrospinal fluid (CSF), a key factor in neurodevelopmental disorders such as cerebral folate deficiency (CFD)." (PMID 40696390, 2025). "The cerebral folate deficiency (CFD) syndrome is defined as any neuropsychiatric condition with low CSF N5-methyltetrahydrofolate (MTHF), where FRα antibodies were identified in the majority of cases, while FOLR1 gene mutations or mitochondrial disorders remain rare alternative causes." (PMID 33294225, 2020).
cervical carcinoma (7 papers, 2020 to 2025). A carcinoma arising from either the exocervical squamous epithelium or the endocervical glandular epithelium. "Folate receptor alpha expression has been associated with cervical carcinogenesis and has been shown to be present in a subset of cervical cancer patients." (PMID 38730739, 2024). "FOLR1 is a member of the folate receptor family, and a previous study showed it is associated with the progression of cervical cancer through the ERK signaling pathway." (PMID 32849815, 2020). "Folate–miR-34a exhibited impressive inhibitory effects on breast, ovarian, and cervical cancer cells that do express FOLR1, suggesting its potential therapeutic application on FOLR1-expressing cancers." (PMID 38396800, 2024). "The tumor-associated antigen, folate receptor alpha is a GPI-membrane protein overexpressed in many malignant tumors of epithelial origin, including ovarian and cervical cancers." (PMID 33414439, 2021). "While our findings expose challenges associated with achieving the specific delivery of folate–miR-34a to PCa, we provide evidence that folate–miR-34a may be a therapeutic agent for FOLR1-expressing cancers including ovarian and cervical cancers." (PMID 38396800, 2024). "Currently, several ADC targets exist (TROP2, mesotheline, CEACAM5, DLL3, folate receptor alpha, guanylatcyclase, glycoprotein NMB, CD56, CD70 and CD138) with ADC compounds being tested in other cancer entities whose expression level in cervical cancer is of clinical interest." (PMID 38730739, 2024).
epilepsy (7 papers, 2014 to 2024). A brain disorder characterized by episodes of abnormally increased neuronal discharge resulting in transient episodes of sensory or motor neurological dysfunction, or psychic dysfunction. "PD, epilepsy, and mild traumatic brain injury showed a significant reduction in FOLR1 but not in folate or FDH, indicating successful folate transfer from blood and into the brain and potential recycling of FOLR1 or its use in transport into the brain for Alzheimer’s disease." (PMID 39337690, 2024).
pancreatic cancer (7 papers, 2015 to 2024). "A previous study identified FOLR1 and DR4 as potential diagnostic markers for pancreatic cancer (PC) patients, showcasing a negative correlation in their expressions." (PMID 38694508, 2024). "Targets for CAR-NK cell treatment in pancreatic cancer includes cGAMP, DR4, and FOLR1." (PMID 38694508, 2024).
mesothelioma (6 papers, 2010 to 2024). A usually malignant and aggressive neoplasm of the mesothelium which is often associated with exposure to asbestos. "FOLR1 expressing human mesothelioma cells lines were used for both in vitro and in vivo studies, both demonstrating FOLR1 targeted cell destruction and tumor growth inhibition through FP mediated PDT." (PMID 33121022, 2020). "Folate receptor alpha was unable to be detected in western blots in any mesothelioma cell line, and was also only barely detectable by real-time PCR." (PMID 20051956, 2010). "This study investigates the response to pemetrexed in a panel of eight mesothelioma cell lines and the clinical outcome for patients treated with pemetrexed in relation to folate receptor alpha (FRα)." (PMID 20051956, 2010). "A similar study also utilized NP delivery in the treatment of mesothelioma by targeting FOLR1." (PMID 33121022, 2020).
pituitary adenomas (6 papers, 2017 to 2025). "Folate receptor alpha (FRα) overexpression has been reported in non-functioning pituitary adenomas." (PMID 40337177, 2025). "OTL38 (On Target Laboratories, West Lafayette, Indiana) is a bioconjugate of a folate analog and a cyanine dye targeting folate receptor alpha (FRα), which may be overexpressed in nonfunctioning pituitary adenomas." (PMID 35344185, 2022).
adenoma (5 papers, 2021 to 2025). A neoplasm arising from the epithelium. "Since OTL38 is folate receptor-alpha targeted (which is mainly expressed in non-functioning adenomas), the sensitivity and specificity was calculated only in non-functioning adenomas with (n = 28) and without (n = 18) overexpression of FRα." (PMID 35344185, 2022). "In fact, previous studies demonstrated that non-functioning adenomas (NFA) usually overexpress folate receptor alpha (FRα) compared to both a normal pituitary gland, hormone secreting functional Pas, and surrounding skull base structures." (PMID 33925235, 2021).
Ataxia (5 papers, 2014 to 2025). Ataxia refers to impaired coordination of voluntary muscle movement. "All of them with FOLR1 mutation presented initial with symptoms such as developmental delay, ataxia, and seizures within the first 3 years of life, and most of them developed motor deficits as well as behavioral abnormalities including autistic behavior." (PMID 25274592, 2014). "Low concentration of 5MTHF in CSF is often found in IGD cases, suggesting that FOLR1 is one of the genes responsible for psychomotor retardation, cerebellar ataxia, and seizures in IGDs." (PMID 38225934, 2024). "One novel variation of FOLR1 was firstly identified from a Chinese male patient with tonic-clonic seizures, developmental delay, and ataxia." (PMID 33243190, 2020).
autism (5 papers, 2016 to 2024). Persistent deficits in social interaction and communication and interaction as well as a markedly restricted repertoire of activity and interest as well as repetitive patterns of behavior. "Biomarkers such as oxidative stress, folate receptor alpha (FRα) autoimmunity, and abnormal brain serotonin turnover are common in autism." (PMID 33294225, 2020).
breast tumors (5 papers, 2015 to 2025). "As with primary breast tumors, the abundance of FOLR1 varies among TNBC cell lines, with a subset expressing high levels." (PMID 25816016, 2015). "We examined the distribution of FOLR1 mRNA using a TCGA RNA-seq dataset from 691 breast tumors classified into basal, Luminal A, Luminal B, and HER2+." (PMID 25816016, 2015). "FOLR1 expression varied within breast tumor subtypes; triple negative/basal tumors were significantly associated with increased expression of FOLR1 mRNA, compared to ER+ and HER2+ tumors." (PMID 25816016, 2015).
colorectal cancer (5 papers, 2016 to 2025). A primary or metastatic malignant neoplasm that affects the colon or rectum. "FOLR1 is frequently overexpressed in solid tumors, where it promotes proliferation, invasion, and poor prognosis; for instance, in colorectal cancer, FOLR1 upregulation facilitates immune evasion via lactate-induced STAT1 lactylation to suppress MHC-I." (PMID 41439026, 2025). "In a study, the combination of an EGFR-targeting oncolytic adenovirus (Onc.Ad-EGFR BITE) with folate receptor-alpha (FR-α)-specific CAR-T cells demonstrated improved tumour cell killing through the secretion of bispecific T-cell engagers (BITE) in pancreatic and colorectal carcinoma." (PMID 40624498, 2025).
glioblastoma (5 papers, 2017 to 2024). The most malignant astrocytic tumor (WHO grade IV). "Analysis of human glioblastoma specimens revealed that at least 25% of glioblastomas express elevated level of either PCFT or folate receptor (FOLR1)." (PMID 31003476, 2019). "Our previous research showed that Folr1 expressed extensively in glioblastoma (GBM) and the level was positively correlated with malignancy grade." (PMID 28416738, 2017). "Analysis of glioblastoma human specimens revealed that a significant amount of tumors express elevated levels of PCFT and/or FOLR1." (PMID 31003476, 2019). "These allow the conclusion that more than 25% of glioblastoma tumors express elevated levels of either one or both of PCFT and FOLR1, respectively, and more than 50% of low grade gliomas overexpress FOLR1." (PMID 31003476, 2019). "Nine human glioblastoma specimens were investigated in order to evaluate the level of gene expression of PCFT (SLC46A1) and FOLR1." (PMID 31003476, 2019).
serous carcinomas (5 papers, 2013 to 2025). "In contrast, ERBB3, FOLR1, and NaPi2b expression levels are higher in serous carcinoma than in endometrioid carcinoma." (PMID 40046734, 2025).
squamous cell carcinoma (5 papers, 2012 to 2021). A carcinoma arising from squamous epithelial cells. "While 74% of adenocarcinomas were positive for folate receptor alpha expression, our results found that only 13% of squamous cell carcinomas were FRA positive (p<0.0001)." (PMID 22547449, 2012).
acute myeloid leukemia (4 papers, 2020 to 2025). Acute myeloid leukemia (AML) is a group of neoplasms arising from precursor cells committed to the myeloid cell-line differentiation. "We recently advanced a FOLR1-specific CAR T-cell product (FH FOLR1-CART) into a trial in infant acute myeloid leukemia (NCT06609928) and now evaluate this CAR construct against osteosarcoma." (PMID 40919994, 2025). "We recently discovered FOLR1 to be expressed in a highly refractory infant acute myeloid leukemia (AML) driven by the CBFA2T3::GLIS2 fusion." (PMID 40919994, 2025).
endometriosis (4 papers, 2018 to 2024). The growth of functional endometrial tissue in anatomic sites outside the uterine body. "In summary, the analgesic capsules can regulate sex hormones in patients with endometriosis, reduce the levels of serum FOLR1 and MSLN, alleviate pain, decrease the size of nodules, improve uterine size, and enhance blood flow in the uterine arteries." (PMID 39465861, 2024). "Comparative analyses encompassed uterine artery hemodynamic parameters, ultrasound (B-mode) findings, Visual Analog Scale scores, traditional Chinese medicine symptom scores, Endometriosis Health Profile-30 scores, and serum levels of FOLR1, MSLN, and sex hormones before and after treatment." (PMID 39465861, 2024). "Examining the impact of Sanjie Zhentong capsules on hormone levels and serum expression of folate receptor 1 (FOLR1) and Mesothelin (MSLN) in endometriosis patients." (PMID 39465861, 2024). "Sanjie Zhentong capsules demonstrate efficacy in regulating sex hormones, reducing serum FOLR1 and MSLN expression, alleviating pain, shrinking adnexal masses, decreasing uterine size, and improving uterine artery blood flow in endometriosis patients." (PMID 39465861, 2024). "In our previous whole-genome expression microarray analysis, we identified that FMO3 was also more specific for the fallopian tube and endometriosis, but not for the endometrium, although the relationship between FOLR1 and FMO3 is unclear." (PMID 36936232, 2023).